PRR20C (proline rich 20C)
Tractability: No criterion of Open Targets' tractability assessment is met for any kind of drug.
Gene: Protein-coding gene on chromosome 13 (57,140,918 to 57,157,082, forward strand). Ensembl gene ENSG00000229665.
Gene Ontology:
Molecular function: protein binding
Homologues: Orthologues: dog PRR20G (38% identical). Paralogues in human: PRR20A (100% identical), PRR20B (100% identical), PRR20D (100% identical), PRR20E (100% identical), PRR20G (53% identical).